ENSG00000276496
Gene: Miscellaneous RNA gene on chromosome 7 (27,186,166 to 27,186,263, forward strand). Ensembl gene ENSG00000276496.
Gene Ontology:
Biological process: negative regulation of gene expression